NLRP3 (NLR family pyrin domain containing 3)
Diseases named in the same sentence as NLRP3 in open-access papers (continued):
Sharing a sentence is not in itself a finding about the gene and the disease.
tumor (continued). "Apart from the NLRP3 inflammasome, other inflammasomes are of importance to suppressing tumor progression." (PMID 37705746, 2023). "Treatment with CX3CR1 mAb also resulted in a reduction of NLRP3 mRNA, a component of the tumor inflammasome." (PMID 37771579, 2023). "The effect of macrophage-mediated depletion of NLRP3 on tumor growth and metastasis was tested in vivo." (PMID 37077909, 2023). "We also have shown that a high level of NLRP3 expression in cancer cells promotes more aggressive tumor features, such as enhanced proliferation and migration, compared to cancer cells that express a lower level of NLRP3." (PMID 36902278, 2023). "Recent reports suggest that the mechanistic link by which MDSCs constrain the immune system response to PD-1/L1 therapy is through the NLRP3/PD-L1 tumor intrinsic signaling pathway." (PMID 37242422, 2023). "MDSC populations and NLRP3 levels were increased with higher tumour recurrent rate in patients using steatotic grafts." (PMID 37916155, 2023). "The reduction of NLRP3 in the S1PR1-KO CD11bhi TAMs group as compared with the WT group decreased IL-1β levels in tumor extracellular fluid more significantly." (PMID 37542283, 2023). "Direct anti-tumor effects of doxorubicin and cisplatin on malignant mesothelioma rely on pyroptosis attributed to increased NLRP3 expression and caspase-1 activation." (PMID 36932407, 2023). "Ovarian tumor deubiquitinase 6 A (OTUD6A) is one of the factors that promoted NLRP3 activation in macrophages." (PMID 37833958, 2023). "In conclusion, this study provides a mechanism by which tumor-mediated NLRP3 activation exploits a distinct adaptive immunity response that facilitates tumor escape and progression." (PMID 37772994, 2023). "The NLRP3-IL-1β pathway from fibroblasts facilitates tumor growth and lung metastasis through intensifying immune suppression, expression of invasive markers in tumor cells, and expression of endothelial cell-derived adhesion molecules." (PMID 36932407, 2023). "NLRP3/IL‐1β overexpressing tumor cells also attracted polymorphonuclear myeloid‐derived suppressor cells." (PMID 38116060, 2023). "In our study, we separately analyzed the expression levels of NLRP3 inflammasome pathway-related proteins in immune-stromal and tumor parenchymal cells." (PMID 38031068, 2023). "Activation of NLRP3 signaling in CAFs facilitated tumor growth and metastasis by modulating immune and endothelial cells." (PMID 37749707, 2023). "Dendritic cell-mediated priming of IFN-γ-producing T lymphocytes against tumor cells requires the NLRP3 inflammasome." (PMID 37715239, 2023). "In CAR-T-cell-treated tumor cells, the robust CAP released a large amount of ATP, which activated NLRP3-mediated inflammasome and pyroptosis in tumor-infiltrating macrophages, leading to the release of cytokines such as IL-1β." (PMID 36742298, 2023). "Inhibiting CD39, an ecto-enzyme converting extracellular ATP to AMP, through antibody activates NLRP3 inflammasomes leading to IL-18 secreting that expands intra-tumor effector CD4+ and CD8+ T cells." (PMID 36932407, 2023). "Before compounds such as IL-1β neutralizing antibodies and IL-18 binding protein can be clinically applied, a deeper understanding of the biological mechanisms of NLRP3 activation, IL-18R- and IL-1R signaling, in regards to tumor progression is needed." (PMID 36766797, 2023). "The activation of an inflammasome in the NLRP3 is one of the most important mechanisms through which tumor growth and metastasis are promoted in BC, which leads to tumor proliferation, angiogenesis, invasion, progression, and recurrence." (PMID 37300757, 2023). "Finally, to address whether the introduction of NLRP3 into NLRP3-deficient NSCLC tumor cell lines would improve ATM activation, we re-expressed NLRP3 using a doxycycline-inducible system in A549 and H292 cells, and evaluated ATM activation after IR by assessing the number of P-ATM and γH2AX foci." (PMID 36746533, 2023).
tumor (continued). "Due to the high similarity between NLRP6 and NLRP3, it is believed that the relationship between NLRP6 and tumor will be as clear as NLRP3 in the future." (PMID 37415625, 2023). "This suggests a significant role for NLRP3 in lowering the anti-tumor response that promotes immunosuppression in patients with lung cancer." (PMID 37893079, 2023). "Among the numerous other microRNAs involved in NLRP3 regulation is miR-22, which acts as a tumor suppressor." (PMID 36834660, 2023). "Several research have revealed The anti-tumor effect of many drugs targeting NLRP3 inflammasomes, including Nigericin and VX-765, was investigated." (PMID 37715239, 2023). "Some recent studies have also confirmed the key role of NLRP3 in MDSC promotion of tumor progression." (PMID 36911674, 2023). "We then retrieved various target genes of NLRP3 from the University of California Santa Cruz (UCSC) database to analyze the molecular mechanisms involved in tumor pyroptosis." (PMID 37864196, 2023). "IL-1β produced by NLRP3 IAP in dendritic cells is required to prime IFN-γ–producing CD8 T cells by dying tumor cells." (PMID 36742298, 2023). "There is considerable evidence suggesting the role of NLRP3 in tumor pathogenesis, although results are often controversial." (PMID 36902278, 2023). "Herein, we also show that NLRP3 activation promotes Th2 polarization, leading to immune suppression and tumor progression." (PMID 37772994, 2023). "Conversely, there is also a report expressing that the NLRP3 inflammasome acts as a tumor suppressor in azoxymethane/dextran sulfate sodium-induced colitis-associated colorectal cancer." (PMID 37524704, 2023). "The NLRP3 inflammasome has been observed to be activated in DCs during chemotherapy and enhanced the anthracycline-induced anti-tumor immune response by secreting caspase-1 and IL-1β." (PMID 37497237, 2023). "Consistent with the findings obtained from tumor-bearing lung tissues, NR1D1 deficiency led to increased mRNA expression of Nlrp3, Il1β, and Il18 in AM, as well as increased protein expression of NLRP3 and cleaved caspase-1 in both AM and normal lung tissues." (PMID 37524704, 2023). "For example, some studies have shown that blocking IL-1β or IL-18 can inhibit tumor growth or metastasis, while others have proven that inhibiting NLRP3 inflammasome can enhance tumor growth or metastasis." (PMID 37715239, 2023). "In summary, our findings indicated that elevated levels of NLRP3/IL‐1β in tumor cells contribute to oxaliplatin resistance and tumor progression through the modulation of PMN‐MDSC recruitment and PD‐L1 expression." (PMID 38116060, 2023). "Our survival and tumor growth data indeed show significant abscopal response with the triple therapy (12Gyx3 + NLRP3 agonist + α-PD1) in both 344SQ-P and 344SQ-R aggressively growing models." (PMID 37289257, 2023). "While important for sensing pathogens, the dysregulated signaling of the NLRP3 inflammasome can induce excess inflammation and has a role in tumor pathogenesis." (PMID 37461742, 2023). "Since MCC950, a specific NLRP3 inflammasome inhibitor, reduced astrocyte-enhanced tumor cell proliferation to the control level, the role of other inflammasome types can also be excluded." (PMID 37749707, 2023). "As a result, NLRP3 signaling has complicated consequences on tumor start and development through modulating antitumor immunity, cell death, proliferation, angiogenesis, and metastasis." (PMID 37715239, 2023). "Previous studies have revealed that NLRP3 inflammasome can positively regulate the proliferation and metastasis of tumor cells, and the activation of NLRP3 inflammasome depends on the production of ROS." (PMID 37153780, 2023). "In melanoma cell line B16-F10, the NLRP3 inflammasome promotes the MDSCs accumulation to counteract anti-tumor immunity." (PMID 37705746, 2023).
tumor (continued). "The mechanism of NLRP3 activation by specific fatty acids was explored in mouse hepatic ischaemia/reperfusion injury (IRI) with tumour recurrence model and in vitro studies." (PMID 37916155, 2023). "NLRP3 also has been reported in a multitude of studies to be involved in tumor growth and development both as an oncogene and as a tumor suppressor gene." (PMID 37449203, 2023). "Genes associated with a pro-inflammatory tumour microenvironment included TNF, IL6, IL18, NLRP3, IL1B and CASP1 which were also comparable between sporadic and NF2-SWN VS samples." (PMID 37680691, 2023). "NanoString analysis of the primary tumor demonstrated that treatments containing XRT + NLRP3 agonist activated multiple immune pathways and genes directly involved in antigen presentation and elevated innate functions." (PMID 37289257, 2023). "In an orthotopic PDAC murine model, genetic and pharmacologic inhibition of NLRP3 significantly reduced tumor growth and weight when compared with the tumor-bearing mice in control." (PMID 37772994, 2023). "Acute Cd exposure induces caspase 3‐GSDME‐mediated pyroptosis to suppress tumor growth of MDA‐MB‐231 breast cancer cells by NLRP3 inflammasome activation and ROS generation." (PMID 37125240, 2023). "The mean RNA transcript level of the NLRP3 was lower in BC tumor samples than in normal tissues in the Cancer Genome Atlas (TCGA) and Genotype-Tissue Expression (GTEx)-derived BC patients." (PMID 36902278, 2023). "Here, we found that lactate, the aerobic glycolysis byproduct released by tumor cells, can directly induce NLRP3 inflammasome activation and promote IL‐1β maturation." (PMID 37009412, 2023). "The upregulation of NLRP3 can either be pro-tumor (colorectal cancer) or a tumor suppressor (hepatocellular cancer), indicating the conversation among signaling pathways, immunity, and genomes in cancer." (PMID 37893166, 2023). "NLRP3 is also expressed in tumor cells and is related to immune resistance through PD-L1/NLRP3 inflammasome signaling." (PMID 37289257, 2023). "At sacrifice, tumor-bearing mice fed with OLT1177 showed a significant reduction in primary tumor mass and weight, similar to what was observed in the Nlrp3−/− mice." (PMID 37772994, 2023). "Further analysis showed that NLRP3 overexpression resulted in the increase of tumor volume and decreased survival rate of HCC xenograft mice, indicating that NLRP3 overexpression counteracted the therapeutic effects of ANI on HCC." (PMID 37153780, 2023). "The NLRP3 inhibitor reduced the amount of active IL-1β to that observed in the control (tumor-free) side." (PMID 37749707, 2023). "P2X7R blockade likely hinders NLRP3 inflammasome-controlled release of tumour-promoting mediators such as IL-1β." (PMID 37225786, 2023). "Owing to these two potentially opposing activities, NLRP3 inflammasome activity has been characterized as a “double-edged sword” within tumors, with a range of studies having ascribed pro- and anti-tumorignenic roles to NLRP3 in particular tumor types." (PMID 37885032, 2023). "NLRP3 inhibition with OLT1177 showed a reduction in tumor volume and weight at 2 weeks from KPC implantation." (PMID 37772994, 2023). "It is suppressing that although many kinds of NLRP3 inhibitors have been invented, only a few of these agents have entered clinical trials for tumor therapy." (PMID 36932407, 2023). "In summary, NLRP3 inflammasome signal seems to promote or suppress tumor metastasis depending on different kinds of tumors and tissues." (PMID 36932407, 2023). "In the tumor cells, Nlrp3 was upregulated 24 h after XRT, with expression peaking following a dose of 6Gy at this time point." (PMID 37289257, 2023). "For example, a pan-cancer analysis has demonstrated that expression levels of NLRP3 can be elevated or dampened in tumor tissues depending on the type of tumors." (PMID 36932407, 2023).
tumor (continued). "LPS stimulation increased PDAC cell viability by regulating the NLRP3 inflammasome and pro-inflammatory cytokines in the tumor microenvironment of PDAC cells/macrophages co-cultures." (PMID 38018872, 2023). "Some studies have shown that NLRP3 accelerates tumor progression by inducing epithelial-mesenchymal transition (EMT) and angiogenesis." (PMID 36902278, 2023). "e-As4S4 significantly inhibited tumor metastasis to the lung and liver by eliminating NLRP3 inflammasomes in tumor tissues." (PMID 37300757, 2023). "As chronic inflammation plays a decisive role in cancer development, NLRP3, IL-18, and IL-1β have been the focus of tumor researchers for over a decade." (PMID 36766797, 2023). "P2X7 receptor plays an important role in the NLRP3/caspase-1 cascade, which can promote tumor proliferation, migration and invasion." (PMID 37020871, 2023). "AIM2 from TAMs and NLRP3 from DCs elicit anti-tumor immune response indicating the therapeutic potential of specifically delivering correspondence activators." (PMID 36932407, 2023). "EMT is an early event of tumor invasion and metastasis; hence, we examined the impacts of NLRP3 knockdown on EMT markers." (PMID 37304662, 2023). "In this study, we report a novel PDAC-mediated inflammatory network that mechanistically links CSF-1 production by PDAC cells to NLRP3 activation in the tumor microenvironment (TME)." (PMID 37772994, 2023). "When the NLRP3 inflammasome is activated, mature IL-1 β and IL-18 are produced, resulting in tumor cell infiltration, metastasis, and angiogenesis." (PMID 37715239, 2023). "Prolonged NLRP3 speck formation favors lung metastasis spread by altering the ability of NK cells to modulate the tumor." (PMID 37891577, 2023). "The cancer-promoting function of NLRP3 is also apparent in the interaction of macrophages with tumor cells which enhances CRC invasion and metastasis." (PMID 37081882, 2023). "Although the demonstration of the anti-tumor properties of this glucocorticoid have also been previously reported, the combination of NLRP3 inhibition and dexamethasone resulted in a marked reduction in tumor volume compared to either treatment alone." (PMID 36672229, 2023). "At the end of their study, the researchers stated that miR-233 activity inhibits the NLRP3 activation pathway, leading to the suppression of tumor cell growth, migration and invasion." (PMID 36834660, 2023). "In many cases, NLRP3 inhibitors are initially invented for the treatment of non-malignant diseases, then these agents are found to be effective in tumor therapies." (PMID 36932407, 2023). "Nigericin displayed an anti-tumor impact in tumor cell lines with modest NLRP3 stimulation and IL-1β and IL-18 production." (PMID 37715239, 2023). "Chemotherapy-induced cell death, like radiotherapy, generates DAMPs such as ATP, which activates the NLRP3 inflammasome and boosts tumor-specific T-cell immunity." (PMID 37415625, 2023). "In tumor settings, activated Nrf2 interferes with Th1eff cells and M1 activation of NLRP3 inflammasome and pro-inflammatory cytokine genes, conferring cytoprotection to tumor cells." (PMID 36670995, 2023). "The attenuated hematopoietic cell-derived IL-1β and IL-18 at the tumor site of Nlrp3−/− mice are found to be the key for inflammation and tumorigenesis." (PMID 36932407, 2023). "The oxidation of tumor cells, also known as oxidative stress, can have a significant impact on tumor growth and invasion, and was found here to be regulated by NLRP3 in intratumoral macrophages." (PMID 37077909, 2023). "Carcinoma cell embolus was found to significantly correlate with high NLRP3 expression in parenchymal cells of the tumor (x2=4.592, P=0.032), while the expression of caspase-1 was negatively correlated with tumor progression." (PMID 38031068, 2023). "Tumor cells were activated by NLRP3 inflammasomes and released lactate dehydrogenase after VTPA treatment." (PMID 37300757, 2023).
tumor (continued). "In AOM/DSS-induced colon cancer, it has been shown that IL-18 levels were decreased in tumor-bearing mice, that the NLRP3/ASC/CASP1/IL-18 axis was important to dampen tumor growth and this was dependent on IFN-γ production." (PMID 37298187, 2023). "Our above data demonstrated that the Arf1‐ablated tumor cells induced activation of the NF‐κB, NLRP3 inflammasome, and cGAS‐STING triple pathways in DCs." (PMID 37786300, 2023). "Previous studies have shown that NLRP3 inhibition reduces MDSC infiltration into the tumor suggesting an additional mechanism for how CX3CR1 mAb blockade can reduce tumor immune evasion." (PMID 37771579, 2023). "Recently, emerging evidence revealed that NLRP3 inflammasome was dysregulated during tumor development." (PMID 37304662, 2023). "NLRP3 leads to the differentiation of tumor-promoting CD4+ T cell subsets (Th2, Th17, and regulatory T cells)." (PMID 37524704, 2023). "Our previous results showed that AL365361.1 was positively correlated with NLRP3, and both of them were positively correlated with anti-tumor immunity." (PMID 36672493, 2023). "We established a subcutaneous tumor mouse model using Hepa1‐6 cells and observed that administration of oxaliplatin had a pronounced effect on inhibiting tumor growth and led to notable upregulation of NLRP3 and IL‐1β." (PMID 38116060, 2023). "Reduction of intestinal IL-18 levels in NLRP3 and caspase-1-deficient mice exposed to AOM/DSS showed that recombinant IL-18 prevented tumor development." (PMID 37081882, 2023). "The tumor-suppressor miR-223 and natural compounds, such as luteoloside and anisonamide, dampen intracellular ROS and suppress NLRP3 activation, modulating HCC cell proliferation and metastasis." (PMID 37891577, 2023). "Over the past few years, wider attention has been paid to the activation of NLRP3 in oncogenic pathways and to the targeted therapeutic approaches based on miRNAs combined with anti-tumor drugs, in order to increase the survival rate of patients." (PMID 36834660, 2023). "Taken together, these data clearly demonstrated that the Arf1‐ablated tumor cells induced NLRP3 inflammasome activation in the co‐cultured DCs." (PMID 37786300, 2023). "A clinic analysis of TCGA revealed that PRKCDBP, Caspase‐1, IL‐1β, NLRP3 and Caspase‐4 were expressed at low level in tumour tissues than in the normal tissues in LUAD and LUSC." (PMID 36696967, 2023). "Tumor cell-derived IL-1β and IL-18 elicited by NLRP3 are responsible for EMT through activating ERK and AKT signal resulting in strengthened migration." (PMID 36932407, 2023). "In metastatic breast cancer, the NLRP3 inflammasome inhibition delays tumor growth by reducing IL-1β in metastatic breast cancer." (PMID 37705746, 2023). "Survival and tumor growth data also showed significant abscopal response with the triple therapy (12Gyx3 + NLRP3 agonist + α-PD1) in both 344SQ-P and 344SQ-R aggressively growing models." (PMID 36824846, 2023). "NLRP3 inflammasome can be activated by various stimuli in the lung microenvironment, such as asbestos, silica, cigarette smoke, hypoxia and tumor-derived factors." (PMID 37715239, 2023). "Activation of the NLRP3 inflammasome complex is associated with the development of inflammatory reactions and TNBC to promote the proliferation and invasion of tumor cells." (PMID 37300757, 2023). "We first explored the efficacy of combining the NLRP3 agonist with different doses of XRT on tumor growth in vivo." (PMID 37289257, 2023). "Although NLRP3 inhibitors alone have shown anti-tumor effects, some attempts highlighted the potential combination of NLRP3 inhibitors with other therapeutic methods." (PMID 36932407, 2023). "In this study, the IC50 values of oxaliplatin and subcutaneous tumor volume were significantly reduced after NLRP3 knockdown or treatment with MCC950." (PMID 38116060, 2023).